KRT17 (keratin 17)
Diseases named in the same sentence as KRT17 in open-access papers (continued):
Sharing a sentence is not in itself a finding about the gene and the disease.
cancer (continued). "Firstly, we utilized siKRT17-3 to investigate if the silencing of KRT17 could impact on cancer properties such as proliferation and colony formation of OSCC cells." (PMID 35706019, 2022). "In conclusion, although KRT17 has been studied in many types of cancer, including BC, our research found that high KRT17 expression correlated with good survival in BC patients with higher HER2 expression but poor survival in patients with lower HER2 expression." (PMID 36139022, 2022). "More and more studies have shown that KRT17 plays a very important role in the occurrence, development and prognosis of a variety of malignant tumours, making it a potential promising biomarker and therapeutic target for a variety of malignant tumours." (PMID 35281081, 2022). "This also indicates that there are multiple ways in which KRT17 acts in malignant tumors." (PMID 35646078, 2022). "To investigate whether KRT17 is involved in regulating cancer stemness in OSCC, we performed sphere-forming assay and inspected for changes in KRT17 expression." (PMID 35706019, 2022). "In addition, we verified KRT17 expression in breast cell lines and found decreased levels in cancer cells (MCF7, MDA-MB-231 and SKBR-3 cells) compared with the normal breast epithelium cell line MCF10A." (PMID 36139022, 2022). "KRT17 is highly expressed in most malignant tumors, suggesting that KRT17 may play a role as an oncogene in cancers." (PMID 35646078, 2022). "KRT17 is mainly expressed in basal epithelial cells and many malignant tumors." (PMID 36300097, 2022). "Among them, Cytokeratin 17 (CK17) promotes cancer progression and epithelial proliferation." (PMID 36004971, 2022). "These preclinical results thus provided a strong support for the in vitro evidence, depicting a novel miRNA-485-5p/KRT17/integrin/FAK/Src/ERK/β-catenin signaling axis that can be exploited for future drug design for cancer stem cell suppression, as well as drug sensitization in OSCC." (PMID 35706019, 2022). "The KRT17 expression was an independent negative survival factor indicating a nearly three times higher risk of disease relapse and cancer specific death (RR=2.50; 95% CI=1.59-3.94; p<0.001)." (PMID 31602265, 2019). "We hypothesized that cellular properties of OSCC are regulated by molecular mechanisms similar to those in the regenerative epithelium, and KRT17 may play a substantial role in the regulation of cancer cell behaviors." (PMID 27512993, 2016). "We determined whether KRT17 works by modulating the nucleocytoplasmic localization of SFN in cancer cells, as has previously been observed in mouse epidermal cells." (PMID 27512993, 2016). "The induction of KRT17 in cancer was confirmed in all the cases." (PMID 27512993, 2016). "Keratin 17 expression was elevated in 62% (98 of 156) of carcinoma samples." (PMID 24962779, 2014). "Therefore, KRT17 in combination with other conventional biomarkers may have a predictive value of cancer recurrence although further validations are necessary." (PMID 38514751, 2024). "The change at this point may be the main reason for the occurrence and development of malignant tumours caused by KRT17, but the specific molecular mechanism is still not clear, and needs further study." (PMID 35281081, 2022). "Cancer 1 and Cancer 2 cells predominantly expressed epithelial markers E-Cadherin (ECAD) and Cytokeratin 17 (CK17), with increased proliferation (Ki67) and glucose uptake (GLUT1)." (PMID 39975273, 2025). "Canonical markers cytokeratin 17 (CK17) for the BL subtype, GATA6 for the CLA subtype, and CK19 as a pan-cancer cell marker are also useful biomarkers." (PMID 40230862, 2025). "Critical hub genes, including KRT16, KRT17, CST1, and CRABP2 emerged as central nodes with high connectivity across multiple cancer-related pathways in both datasets." (PMID 40725485, 2025). "We identified a metastasis-related cancer cell subset EP1, which was characterized with a high expression of KRT17, LAMC2, EMP1, and PLAC8." (PMID 38818308, 2024).
cancer (continued). "COL17A1, KRT15, KRT17, S100A2, SFN, which have been shown to assume oncogenic roles in various cancers, were among the highly changed genes and positively correlated with p63 expression." (PMID 38012140, 2023). "Top up-regulated genes related to cancer were: (i) IL-20, CLK1, SORBS2, ERG1, PIM1, SNORD3A for normal FHC cells and (ii) TSLP, BHLHA15, LAMP3, ZNF27B, KRT17, ATF3 for cancerous HT29 cells." (PMID 38033043, 2023). "We used the canonical markers cytokeratin 17 (CK17) for the basal subtype, GATA6 for the classical subtype, and cytokeratin 19 (CK19) as a pan-cancer cell marker." (PMID 36781852, 2023). "In the 178 PC patients, the LAMB3, FN1, KRT17, KRT19, and ANXA1 were also upregulated in cancer tissue, compared with adjacent tissues and normal tissues." (PMID 35428170, 2022). "Recently, altered expression of several keratins including keratin 6 (KRT6), KRT14, KRT15, KRT16, KRT17 and KRT19 were reported to coordinate tumorigenesis in different types of cancers." (PMID 35706019, 2022). "Then, we analyzed the upregulated top five differentially expressed genes between the paracancer tissue and the cancer tissue, which included LAMB3, FN1, KRT17, KRT19, and ANXA1." (PMID 35428170, 2022). "Two genes, KRT17 and ECM1, which expression was elevated in our TERTp(+) PTCs, demonstrated higher expression in a variety of cancer types." (PMID 32560331, 2020). "Second, it remains unclear whether clinical variables, such as age, sex, or cancer stage, affect KRT6A and KRT17 expression in human MG and MGC, which should be evaluated in a larger cohort." (PMID 41439999, 2025). "Keratin 17 has been reported to be a negative prognostic biomarker for several types of cancer, including squamous cell carcinoma of the lungs (LSCC) and pulmonary adenocarcinoma (LUAD)." (PMID 39194725, 2024). "We investigated the protein expression of KRT17 in the HPA database, and we obtained IHC images of 19 types of cancer tissues and corresponding normal tissues; we also obtained corresponding clinicopathological parameters, such as patient ID, sex, age, and antibody." (PMID 35646078, 2022). "Keratin17 (KRT17) has been proven to serve as an oncogene in various cancers, but it has never been explored in LSCC." (PMID 36248412, 2022). "For example, although the keratin genes (KRT5, KRT14, and KRT17) were found to interact in cancer genome studies, it was not clear how the cluster affects clinical features for cancer." (PMID 37395630, 2022). "Therefore, we used the Quantiseq, Xcell, Mpcounter, and EPIC methods to analyze the relationship between KRT17 expression and the infiltration of macrophages, CD8+T cells, Tregs, and cancer-related fibroblasts." (PMID 35646078, 2022). "Similarly, S100A2, KRT14, KRT17, and KRT6A were overwhelmingly expressed in cancer cells and their expression values were significantly higher than the other cells (log10FC > 3 and P < 0.001)." (PMID 34326696, 2021). "We previously reported a novel negative prognostic biomarker, keratin 17 (K17), whose overexpression in cancer results in shortened patient survival." (PMID 32533886, 2020). "We determined whether ITGBL1 regulated the KRT17 expression through TGF‐β1 signalling pathway, which also induces the epithelial‐mesenchymal transition (EMT) in various types of cancers." (PMID 32537856, 2020). "The 5-year cancer specific survival rate for the KRT17 positive and negative group was 65.2% and 91.5%, whereas the 10-year survival rate was 36.4% and 78.3%, respectively." (PMID 31602265, 2019). "Like keratin 9, keratin 17 is not expressed in normal mature epithelia; however, it is expressed in ectodermal embryonic stem cells and in carcinomas." (PMID 29802537, 2018). "In addition, fibroblasts (n = 1 068) were identified by COL1A1 and FAP, endothelial cells (n = 2 561) were positive for RAMP2 and CLDN5 expression, smooth muscle cells (n = 1 100) were defined by TAGLN and CNN1, and epithelial/cancer cells (n = 319) were labeled by KRT14 and KRT17." (PMID 40360503, 2025).
cancer (continued). "In addition, the high expression level of KRT17 has been shown to be closely relevant to the advancement of epithelial-mesenchymal transformation (EMT), proposing another crucial portion in accelerating cancer cell survival and metastasis." (PMID 36248412, 2022). "To date, there have been no reports of KRT17 in pan-cancer studies." (PMID 35646078, 2022). "KRT17 is regarded a “stress-response keratin” that is not expressed or at a very low level in normal squamous epithelium and is induced under pathological conditions, such as wound healing, inflammation, and cancer." (PMID 32012175, 2020). "We previously identified Keratin 17 (K17) as a negative prognostic biomarker in other cancer types." (PMID 31375762, 2019). "Thus, KRT17 could be used to rule out those without cancer recurrence more accurately especially after 6 to 12 months after TUR." (PMID 38514751, 2024). "These genes included AGR2, KRT17, SPDEF, and LAD1 which were expressed in EV-RNA of patients 5 and 15 and of all cancer cell lines, but not in HBDs." (PMID 33761899, 2021).
infection (14 papers, 2015 to 2025). The state of being infected such as from the introduction of a foreign agent such as serum, vaccine, antigenic substance or organism. "Some up-regulated genes at 21 dpi (e.g., Ltf, Cxcl9, Pglyrp1, Prg2, Cxcl13, Cxcl3, Ccl9, Ccl19, Krt5, Krt14, Krt15, Krt17, and Slpi) were also identified in a previous infection study by using H1N1(PR8)." (PMID 38005876, 2023). "In this report, we identified a new host factor, stress keratin 17, which contributes to MmuPV1 infection-induced cutaneous papillomatosis by modulating the host cellular immune response to MmuPV1 infection." (PMID 31968015, 2020). "However, MmuPV1 E7 expression led to a significant accumulation of stress keratin 17, a marker associated with immune evasion and elevated in both HPV16 transgenic models and MmuPV1 infections." (PMID 41165329, 2025). "Our laboratory recently discovered that stress cytokeratin 17 is one of the most upregulated host genes upon cutaneous MmuPV1 infection and that K17 plays an important role in mediating the ability of the virus to evade immune clearance and establish persistent disease." (PMID 32398315, 2020). "Stress keratins have been previously shown to be increased during MmuPV1 infection in immunocompetent FVB/N mice, with Krt17 playing a key role in inhibiting T cell response." (PMID 41165329, 2025). "Studies have shown that KRT17+ hair follicle organoids can be infected by SARS‐CoV‐2, showing impaired hair follicle and epidermal development, infection of nervous system cells, and death of neurons." (PMID 39309690, 2024). "A second theory states that HSIL is the result of a hrHPV infection of IMM, as concluded from the dual expression of keratin 17 and p16 in atypical squamous lesions with metaplastic features." (PMID 32644288, 2020). "Furthermore, proteins related to the cytoskeleton and cytoskeleton remodeling (KRT2 and PLXNA4) and genes coding for components of the cytoskeleton, KRT13 (LOC100515166), KRT17 (LOC100737113), KRT6A, and BFSP1, were significantly higher expressed after infection with swH1N1 compared to huH1N1." (PMID 39247193, 2024).
bacterial infection (1 paper, 2008). "Of these, only 3 genes (CA3, KRT17 and PLN) have been annotated, and none of these previously have been shown to be involved in the response to bacterial infection." (PMID 18811943, 2008).
immune disorder (1 paper, 2022). "KRT17 blocks T-cell infiltration to induce an inflammatory microenvironment and immune disorder." (PMID 36532504, 2022).
inflammation (1 paper, 2012). Aberrant reaction of the microcirculation characterized by movement of fluid and leukocytes from the blood into extravascular tissues. "Altogether our data raise the possibility that cytochrome b5 and cytokeratin 17 are potential biomarkers of lung injury released from damaged epithelium early during pulmonary inflammation." (PMID 22792238, 2012).
KRT17 also shares sentences with these, for which no sentence is quoted: skin cancer (10 papers); dysplasia (6); prostate carcinoma (5); adenocarcinoma (4); allergic contact dermatitis (3); atopic dermatitis (3); cervical intraepithelial neoplasia (3); epidermolytic hyperkeratosis (3); Erythema (3); hidradenitis suppurativa (3); invasive carcinoma (3); leukoplakia (3); lichen planus (3); papillary thyroid carcinoma (3); staphylococcus aureus infection (3); acne (2); adenocarcinoma of gallbladder (2); Autoimmunity (2); benign tumor (2); chronic cervicitis (2); colon adenocarcinoma (2); cutaneous papillomas (2); gallbladder cancer (2); hepatocellular carcinoma (2); ichthyosis (2); keratinization disorders (2); laryngeal squamous cell carcinoma (2); metastasis (2); psoriasis vulgaris (2); renal carcinoma (2).
A further 83 diseases each share a sentence with KRT17 in 2 papers or fewer.